BCL2 (BCL2 apoptosis regulator)
Diseases named in the same sentence as BCL2 in open-access papers (continued):
Sharing a sentence is not in itself a finding about the gene and the disease.
Thrombocytopenia (continued). "SMI toxicity varies by type: pan BCL-2 homology domain 3 (BH3) mimetics (AT-101) tend to be more toxic, causing dose-dependent thrombocytopenia, selective BCL-2 BH3 mimetics, although platelet sparing, induce resistance and increase the risk of tumor lysis syndrome." (PMID 27283896, 2016). "One consideration in using ABT263 is its mechanism of action, which involves the inhibition of antiapoptotic proteins like Bcl‐xL and Bcl‐2, known to induce platelet apoptosis and lead to thrombocytopenia." (PMID 39931736, 2025). "First, the patient had profound thrombocytopenia and coagulopathy following induction chemotherapy, which are known adverse effects of hypomethylating agents and BCL-2 inhibitors." (PMID 40951121, 2025). "Compared to other BCL-2 inhibitors (such as Navitoclax), VTC has higher selectivity towards BCL-2, reducing the risk of thrombocytopenia and yielding better therapeutic outcomes with milder adverse effects." (PMID 38026941, 2023). "A major drawback of earlier BH3 mimetics targeting multiple Bcl-2 proteins, such as navitoclax, was their on-target/off-tumor inhibition of Bcl-xL in platelets, resulting in dose-limiting thrombocytopenia." (PMID 36672426, 2023). "The combined Bcl-2/Bcl-xL inhibitor ABT-263 showed in clinical trials dose-limiting side effects with thrombocytopenia, attributed to inhibition of Bcl-xL, and leukocytopenia, due to Bcl-2 inhibition." (PMID 35887198, 2022). "As a small molecule targeted drug, selective Bcl-2 inhibitors VEN overcome the problem of thrombocytopenia, which brings new treatment options to patients with hematological malignancies." (PMID 36477747, 2022). "The side-effects, especially thrombocytopenia, as well as the introduction of venetoclax as a specific BCL-2 inhibitor, have somewhat halted the introduction of navitoclax." (PMID 36430230, 2022). "Despite consistent side effects for Navitoclax, which included thrombocytopenia, based on Bcl-xL expression-dependency for platelet survival, it was effective at killing Bcl-2-dependent CLL cancers, just as effectively as ABT-737." (PMID 34753495, 2021). "Venetoclax, a newly orally available and selective BCL2 inhibitor, has shown great effectiveness in various haematologic malignancies, with less thrombocytopenia observed." (PMID 34956909, 2021). "The thrombocytopenia associated with ABT-263 is linked to BCL-XL inhibition and can be avoided with ABT-199 which is specific to BCL2." (PMID 33494434, 2021). "In fact, thrombocytopenia is one of the main dose-limiting toxicities of the oral Bcl-2/Bcl-xL inhibitor, navitoclax." (PMID 33495510, 2021). "More effective for in vivo use, ABT-263 mainly inhibits BCL-2 and BCL-xL, whereas it frequently causes thrombocytopaenia." (PMID 34873338, 2021). "Whereas leukopenia was mainly attributed to the inhibition of BCL-2, inhibition of BCL-XL is presumably the major cause of thrombocytopenia observed upon ABT-263 treatment." (PMID 33070156, 2020). "Venetoclax (ABT-199) was developed to specifically inhibit BCL2 with only weak activity towards other members of the BCL2 family, including BCLxL thereby minimising thrombocytopaenia as a dose-limiting toxicity." (PMID 35582439, 2020). "Current limitations of this strategy are risks of navitoclax (ABT-263) inducing thrombocytopenia and neutropenia due to Bcl-2 and Bcl-xL inhibition, respectively." (PMID 32630281, 2020). "Earlier clinical studies have shown that the combined BCL-2/BCL-XL/BCL-W inhibitor, Navitoclax (ABT-263) induces severe thrombocytopenia caused by direct platelet demise and counteracted by increased megakaryopoiesis." (PMID 31907357, 2020). "A dual inhibitor of Bcl2 and Bcl-XL, named Navitoclax (ABT-263), resulted to be cytotoxic in Bcl2-dependent neoplasia, but it induced excessive cell toxicity during clinical trials, resulting in thrombocytopenia, and thus limiting its clinical application." (PMID 33255367, 2020).
Thrombocytopenia (continued). "As thrombocytopenia was caused by BCL-XL inhibition, the BCL-2-specific inhibitor, venetoclax, is a good candidate to control SCLC." (PMID 32152266, 2020). "After navitoclax demonstrated dose-dependent thrombocytopenia, navitoclax was re-engineered into venetoclax, which is specific for BCL-2." (PMID 29854301, 2018). "The results of the phase I study of Navitoclax (ABT-263, disruptor of BCL2–BCL-xL interactions with pro-apoptotic proteins) in patients with relapsed or refractory CLL were more promising, but it caused thrombocytopenia due to BCL-xL inhibition." (PMID 24337970, 2015). "Venetoclax selectively binds Bcl-2 without causing thrombocytopenia, and showed promising preclinical results." (PMID 37870696, 2023). "However, AstraZeneca has recently developed AZD0466, a dual Bcl-2/Bcl-xL inhibitor conjugated to a PEGylated poly-lysine dendrimer, that has reduced the cardiovascular issues and thrombocytopenia seen with other Bcl-2/Bcl-xL inhibitors." (PMID 37163552, 2023). "For example, treatment with the BCL-2 inhibitor and a senolytic drug ABT-263 causes transient thrombocytopenia, which may reflect the fact that mature megakaryocytes themselves appear to be physiologically senescent cells." (PMID 35951353, 2022). "After an initial positive assessment on multiple cellular lines, where ABT-263 reported stronger inhibitory actions, presumably by targeting both BCL-xL and BCL-2, advanced clinical studies unfortunately revealed major physiological pitfalls such as thrombocytopenia." (PMID 35252355, 2022). "One of the major issues of previous Bcl2 inhibitors has been thrombocytopenia." (PMID 35885991, 2022). "Venetoclax, a BCL-2 -selective inhibitor, has shown potent activity in inhibiting the growth of BCL-2-dependent hematological cancers but spares platelets, thus avoiding pronounced thrombocytopenia caused by BCL-XL inhibition." (PMID 34778088, 2021). "However, preclinical data of ABT263 suggested dose-limiting thrombocytopenia, which was overcome by the development of selective BCL2 inhibitor ABT199." (PMID 33976278, 2021). "ABT-199 (venetoclax) has been designed to be selective to BCL-2 and thus does not cause thrombocytopenia." (PMID 33920941, 2021). "While one BCL-2 selective inhibitor (venetoclax) is approved, BCL-2, BCL-XL dual inhibitors such as ABT263 are limited due to on-target inhibition of BCL-XL in platelets that causes thrombocytopenia." (PMID 33839157, 2021). "Venetoclax is a second-generation BH3 mimetic with higher selective inhibition of BCL2 over BCL-XL as compared to the first generation BH3 mimetic navitoclax, thus reducing the off-target effect of thrombocytopenia seen with BCL-XL inhibition while retaining strong BCL2 inhibition." (PMID 32552760, 2020). "It was therefore hypothesized that a BCL-2 selective inhibitor should exhibit limited thrombocytopenia while maintaining antitumor activity in BCL-2 dependent lymphoid malignancies." (PMID 29732004, 2018). "ABT-199 (venetoclax) is a potent, specific BCL-2 inhibitor that does not inhibit other anti-apoptotic molecules and avoids the thrombocytopenia associated with inhibition of BCL-XL." (PMID 26862853, 2016). "However, once in clinical trials, the orally bioavailable BCL-2/BCL-xL antagonist ABT-263 (Navitoclax) was found to have dose-limiting toxicity of thrombocytopenia, as a result of the induction of platelet death." (PMID 27140313, 2016). "However, ABT-737 and ABT-263 can induce thrombocytopenia due to their inhibitory effects on both Bcl2 and Bcl-XL." (PMID 26682258, 2015). "This is even a problem with BH3 mimetics: (i) most putative mimetics act through off-target effects and (ii) the bona fide BH3 mimetic ABT-263 antagonizes both Bcl-2 and Bcl-xL, so that inhibition of Bcl-xL activity results in toxic thrombocytopenia in patients." (PMID 24525395, 2014).
Thrombocytopenia (continued). "BCL-XL/BCL-2 co-dependent cell lines could be targeted with navitoclax, however, the clinical translation of navitoclax is hampered by dose-limiting on-target toxicity of thrombocytopenia." (PMID 36588105, 2023). "The development of the pan-Bcl-2 inhibitor obatoclax has been ceased due to low response rates and neurologic and psychiatric side effects, and the use of navitoclax, which not only inhibits Bcl-2 but also Bcl-xL and Bcl-w, is limited due to acute, dose-dependent thrombocytopenia." (PMID 26927160, 2016). "ABT-199 (venetoclax) is a next-generation BH3 mimetic designed to spare BCL-xL; however, despite the obvious benefit of this drug in avoiding thrombocytopenia, its utility may largely be dictated by a cancer's propensity to rely on BCL-2 over BCL-xL for survival." (PMID 26859456, 2016). "Since ABT-199 did not cause thrombocytopenia in vivo, this suggests that selective inhibition of Bcl2 may benefit the development of improved Bcl2 antagonists." (PMID 26682258, 2015). "Other potent senolytics include navitoclax (ABT-263), which targets BCL-2/BCL-xL anti-apoptotic signaling, but it has shown dose-limiting thrombocytopenia in preclinical and early clinical trials." (PMID 40823556, 2025). "Recognition of this dual BCL-2/BCL-xL dependence has prompted several ALL trials combining venetoclax with low-dose navitoclax to enhance therapeutic efficacy without the dose-limiting thrombocytopenia associated with navitoclax monotherapy (NCT03181126, NCT05192889)." (PMID 38600316, 2024). "Navitoclax, a BH3 mimetic that inhibits both BCL2 and BCL-XL, was the first potent BCL2 inhibitor to enter clinical trials; however, profound thrombocytopenia proved to be the dose-limiting toxicity due to the critical role of BCL-XL in platelet survival." (PMID 39684800, 2024). "Despite VTC’s pronounced affinity for BCL-2 over BCL-XL and BCL-W, thrombocytopenia remains a prevalent side effect during treatment." (PMID 38026941, 2023). "We investigated some apoptotic markers (caspase 3, caspase 8 and BCL2) using the flow cytometry in 60 children with newly diagnosed ITP, 20 children with chemotherapy-related thrombocytopenia (CRT) and 20 healthy children." (PMID 37786823, 2023). "The simultaneous inhibition of BCL-2 and BCL-XL led to a reduction in thrombocytopenia and other side effects induced by navitoclax, which ensured treatment effectiveness." (PMID 38069030, 2023). "Several other phase I trials confirmed the efficacy of ABT-263, but patients exhibited signs of thrombocytopenia and T-cell lymphopenia due to the inhibition of BCL-XL and BCL-2, respectively." (PMID 39872303, 2023). "Despite having a high affinity to BCL-2, BCL-XL, and BCL-W, the clinical use of navitoclax (ABT-263) has been restricted by the on-target toxicity of thrombocytopenia." (PMID 38069030, 2023). "A phase I and a phase II study with navitoclax, a selective inhibitor of Bcl-2 and Bcl-x, showed limited activity in advanced and recurrent SCLC with a high rate of serious thrombocytopenia." (PMID 37870696, 2023). "ABT-263 induces dose-limiting thrombocytopenia due to platelets requiring BCLXL for survival, and BCL2/BCLXL also regulate monocyte/macrophage and neutrophil survival; we therefore examined the effect of cycles of ABT-263 on blood counts." (PMID 34142149, 2022). "We found eight proteins (ITGA2B, ITGB3, VWF, PLEK, TNF, TLR2, BCL2 and BCL2L1) were the core targets of DMAG for the treatment of thrombocytopenia." (PMID 34837956, 2021). "Navitoclax, the first anti-BCL2 small molecule, demonstrated high efficacy in R/R CLL patients but its use was limited by severe thrombocytopenia." (PMID 32164276, 2020). "The synergy between DT2216 and ABT199 is potentially greater than dual inhibition of Bcl-xL and Bcl-2 by ABT263, which also induces dose-limiting thrombocytopenia in humans." (PMID 32677976, 2020).
Thrombocytopenia (continued). "The turning point in the research for Bcl-2 inhibitors was reached with the development of venetoclax, a potent and selective BH3 mimetic for Bcl-2 protein, which was able to circumvent the thrombocytopenia observed with navitoclax." (PMID 32455818, 2020). "Previous clinical studies of BCL2/Bcl-xL inhibitor navitoclax in patients with CLL and small cell lung cancer demonstrated thrombocytopenia as a major dose-limiting toxicity, which would militate against the use of navitoclax in combination with ABBV-07550,51." (PMID 30647404, 2019). "Early efforts in BCL2 inhibitor including ABT-737 and ABT-263/navitoclax were encountered with disappointment in clinic because of dose-dependent thrombocytopenia." (PMID 31253168, 2019). "MCL-1 is the preferred target, as agents such as Navitoclax that target both BCL-2 and BCL-XL, have resulted in platelet toxicity and dose limiting thrombocytopenia." (PMID 30701031, 2018). "Navitoclax was re-engineered to create a more selective BCL-2 inhibitor, venetoclax (ABT-199), which also acts as a BH3 mimetic but shows higher specificity for BCL2 and lower specificity for BCL-XL, decreasing the rate of thrombocytopenia." (PMID 26393619, 2015). "BCL‐2/BCL‐xL inhibitor inducing mitochondrial apoptosis; limited by thrombocytopenia." (PMID 41591255, 2026). "Indeed, we found that romiplostim pre-treatment for 4 days prior to the daily administration of the BCL-2 and BCL-XL inhibitor ABT-263 raised platelet production and prevented treatment-induced thrombocytopenia." (PMID 41507122, 2026). "Its superior efficacy, along with fewer side effects—attributable to selective BCL2 inhibition without inducing thrombocytopenia or damaging healthy tissue —support its preference over Navitoclax for AP therapy." (PMID 40715042, 2025). "Other senolytics include navitoclax (ABT-263), an inhibitor that targets anti-apoptotic members of the BCL-2 family, particularly BCL-2, BCL-W that restores the apoptosis of senescent cells, though its clinical use is limited by dose-dependent thrombocytopenia." (PMID 41302153, 2025). "Similarly, the dual BCL-2/BCL-xL inhibitor pelcitoclax, exploiting a prodrug strategy, has shown promising results in reducing thrombocytopenia while maintaining efficacy against metastatic solid tumors." (PMID 40973765, 2025). "However, dose-limiting thrombocytopenia, due to on-target BCL-xL inhibition, discouraged its further development which was superseded by the selective BCL-2 inhibitor venetoclax." (PMID 38600316, 2024). "As thrombocytopenia is an established on-target toxicity of BCL-XL inhibition, we also examined the effect of combining encorafenib with the BCL-XL -targeting PROTAC DT2216, and the novel BCL-2/BCL-XL inhibitor dendrimer conjugate AZD0466." (PMID 38429301, 2024). "BCL-2 family proteins have proven to be outstanding targets for cancer therapy, but their importance in controlling normal cell survival often leads to dose-limiting on-target toxicity of BCL-2 inhibitors that induce neutropenia or diarrhea, or BCL-XL inhibitors that result in thrombocytopenia." (PMID 39872303, 2023). "Although the early non-selective Bcl-2 inhibitor has shown good antitumor activity in clinical trials, it can also act on Bcl-XL, which will lead to severe thrombocytopenia." (PMID 36477747, 2022). "However, outcomes were disappointing and this failure was attributed to the dose-limiting thrombocytopaenia from BCL-XL co-inhibition, restraining the magnitude of BCL-2 inhibition achievable." (PMID 34581776, 2021). "Dual BCL-2/BCL-XL inhibitors are anticipated to deliver therapeutic benefit in many hematological and solid cancers, but their clinical development has also been limited by tolerability and safety issues including thrombocytopenia." (PMID 34073507, 2021).
Thrombocytopenia (continued). "Regarding BCL2 proteins, venetoclax is a novel BCL2 inhibitor which resolved some of the complications of previous BCL2 inhibitors, like having no difficulties in the circulation of the platelets and thrombocytopenia." (PMID 39811307, 2025). "However, ABT-737, like navitoclax, has demonstrated hematologic toxicity in vivo, including thrombocytopenia and neutropenia, due to the on-target depletion of non-senescent cells that rely on BCL-2/XL signaling for survival." (PMID 40563501, 2025). "Navitoclax is known to induce dose-limiting thrombocytopenia, which has been attributed to its targeting of BCL-XL, yet intermittend or lower navitoclax dosing and novel dual BCL-2-/BCL-XL inhibitors show promising clinical potential, as these strategies may provide better tolerance." (PMID 38942989, 2024). "This strongly suggests that the magnitude of BCL-2 inhibition was limited in this trial by the toxicities induced by the BCL-XL targeting of navitoclax, and treatment with a BCL-2 specific inhibitor would be expected to avoid thrombocytopenia and therefore more potently inhibit BCL-2." (PMID 37685889, 2023). "Navitoclax, which inhibits BCL-2/BCL-XL/BCL-W, has been extensively tested in lymphoid malignancies and myeloproliferative neoplasms; however, its applicability in AML has proven to be limited due to significant thrombocytopenia, since platelets solely depend on BCL-XL for survival." (PMID 36291779, 2022). "AstraZeneca’s dual Bcl-2/Bcl-xL inhibitor, AZD4320, was intended as an intravenously administered drug with an intermittent dosing schedule, with the aim of achieving rapid Bcl-2/Bcl-xL inhibition in tumour cells whilst enabling recovery from on-target thrombocytopenia between dosing." (PMID 33495510, 2021). "Because long‐term treatment with a senolytic drug may be required to prevent/treat age‐related diseases and extend lifespan, there is a concern that Bcl‐2/xl/w inhibitors might be not safe for humans because of their known on‐target (thrombocytopenia) and off‐target toxicities." (PMID 29766639, 2018). "ABT-263 is known to induce thrombopenia due to reduced platelet lifespan; however, the next generation dual inhibitors of Bcl-XL and Bcl-2, such as AZD4320, have been reported to not induce dose-limiting thrombocytopenia and, therefore, would be more suitable for a clinical application." (PMID 35056150, 2022).